IDH1 (isocitrate dehydrogenase (NADP(+)) 1)
Diseases named in the same sentence as IDH1 in open-access papers (continued):
Sharing a sentence is not in itself a finding about the gene and the disease.
glioma (continued). "In conclusion, modified amounts of active SIRT1, IDH1 and MDH1 in gliomas may interfere with acetyl-CoA production." (PMID 21655185, 2011). "A recent meta-analysis suggested that IDH1 and IDH2 mutations are significantly associated with an increased incidence of preoperative seizures in low-grade (II) but not in high-grade (III and IV) gliomas." (PMID 40103938, 2025). "In this milieu, D-2HG produced by mu/IDH1 may enhance neuronal activity by mimicking the action of glutamate on NMDA receptors, thereby increasing the propensity for seizures in patients with mu/IDH1 gliomas." (PMID 40182999, 2025). "Inhibitors which selectively bind mut-IDH1 and not wt-IDH1, so far lacking, could be excellent drug leads against glioma." (PMID 40569935, 2025). "Our investigation revealed elevated LSM2 expression in gliomas through exploration of the TCGA database, LSM2 expression is significantly higher in GBM compared to lower-grade gliomas (LGG), and its expression correlates with the presence of IDH1 mutations and the 1p/19q non-deletion status." (PMID 40365337, 2025). "However, for IDH1-mutant (IDH1_MT) glioma cases (n = 182), age at disease diagnosis had no significant impact on PFS rates (p = 0.89)." (PMID 38267516, 2024). "Low-grade gliomas in children rarely transform into high-grade tumors, unlike adult gliomas, in which the presence of the IDH1 and IDH2 mutations may influence the development of high-grade gliomas." (PMID 38612890, 2024). "The CT2A glioma line extensively leveraged in this work may already harbor intrinsic tumor-related molecular mechanisms independent of ATRX loss and mutant IDH1 that may impact immune microenvironmental engagement." (PMID 38272925, 2024). "No gliomas were found in the brains of Idh1-mu mice during the observation." (PMID 39872214, 2024). "However, oligodendroglioma is defined by the co-occurrence of mutations in the IDH1 or IDH2 genes and 1p/19q codeletion, which are absent in F3T3 gliomas." (PMID 38730596, 2024). "Our results clearly indicate a potential for successful transfer of our method towards IDH1 wildtype glioma; however, validation is limited due to the current lack of specific histopathological tumor-cell markers that can be combined with other markers in multiplexed immunhohistochemistry." (PMID 38263411, 2024). "Interestingly, the IDH1 mutant glioma was the tumor that did not conform to this trend, suggesting that it has a distinct metabolic profile from the primary GBMs, but still harbors an astrocyte-like subpopulation that is selectively vulnerable to ferroptosis." (PMID 39192032, 2024). "Gliomas with Isocitrate dehydrogenase 1 (IDH1) mutation are associated with better outcomes and are more responsive to temozolomide (TMZ) compared to those without IDH1 mutation." (PMID 38982076, 2024). "As such, while further studies are needed to firmly establish the extent and time-course of accumulation in IDH1 mutated brain tumors, the available data suggest that [18F]AG120 may not be an optimal candidate for glioma imaging in patients." (PMID 37049661, 2023). "A window-of-opportunity trial of vorasidenib and the IDH1 inhibitor ivosidenib randomized patients with recurrent nonenhancing WHO 2016 grade 2 or 3 IDH1mt glioma who were undergoing craniotomy to receive either ivosidenib, vorasidenib, or no treatment for 4 weeks preoperatively." (PMID 36968138, 2023). "Although dogs remain a valuable animal model for comparative studies of glioma, our study adds additional evidence of important differences in glioma biology between dogs and humans, because we did not identify associations between T2FMM and astrocytomas in dogs or the presence of IDH1 mutations." (PMID 37246729, 2023). "This explains why most mutant IDH1/2 gliomas are not grade IV, while most wild-type gliomas are." (PMID 37280670, 2023).
glioma (continued). "Ivosidenib could prolong the survival of mice bearing GL261 glioma tumor with mutant IDH1, but did not change the survival of mice bearing wild-type GL261 glioma tumor." (PMID 37741882, 2023). "Together, according to our analysis, high FAP expression predicts a poorer prognosis for glioma patients, elevated FAP expression correlates with non‐codeletion of 1p19q, wild‐type IDH1 status, and old age, and FAP might serve as a biomarker for predicting overall survival." (PMID 36382346, 2023). "In addition, neutralizing neutrophils by using a monoclonal antibody against Ly6G resulted in increased survival of an IDH1–wild-type (WT) glioma model, but not an IDH1-mutant (MUT) PDGFB-driven glioma mouse model." (PMID 36594465, 2023). "Interestingly, Drews and colleagues also noted a significant negative association between mutant IDH1 and CIN signature 1 in a pan-cancer analysis, strengthening our observation in grade 4 gliomas." (PMID 38260852, 2023). "However, the mechanism of cell death pathways (e.g., altered autophagic flux) in IDH1 mutant gliomas is not well elucidated." (PMID 37476290, 2023). "While in IDH wildtype glioblastoma CDKN2A deletions are nearly universally homozygous, we acknowledge that in some patients with IDH1/2mt gliomas, the CDKN2A deletion as determined by NGS may not be homozygous." (PMID 36968138, 2023). "Therefore, finding the DEGs between IDH1 MUT and WT GBM, especially the metabolic related DEGs, will help to explain the reasons for the different prognosis between these two pathological types of gliomas." (PMID 36389748, 2022). "Additionally, IDH1, R132H, and PPM1D mutant gliomas have been shown to selectively rely on NAD salvage pathways, suggesting these sub-populations of tumors may benefit from NAMPT inhibition." (PMID 35814452, 2022). "Importantly, AGI-5198 inhibits the growth of mIDH1 glioma but has no significant inhibitory effect on IDH1 wild-type gliomas." (PMID 36091829, 2022). "The average survival time of GBM patients is about 15 months and the 5-year survival rate is less than 5%.7–11 In clinic, majority of GBM patients (about 90%) are diagnosed with wild-type IDH1/2 and have no glioma history, which is defined as primary or de novo GBM." (PMID 35105853, 2022). "In addition, our results showed that KIF2C was higher in IDH1 wild-type samples than IDH1 mutant glioma samples, and KIF2C was higher in 1p/19q noncodel samples than 1p/19q code glioma samples." (PMID 35387222, 2022). "Of the 56 cases of gliomas, IDH1 R132H mutant protein expression was seen in the neoplastic glial cells in 16 (28.6%) cases, while the majority (n = 40, 71.4%) were completely negative for the IDH1 R132H mutant protein." (PMID 36292072, 2022). "Therefore, further restricting the FGFR1 sequencing analysis to non-diffusely growing gliomas/MNGT tumors would yield 15% FGFR1 N546/K656 mutant cases after exclusion of cases with BRAF fusion, IDH1/2, NF1 or TERT mutation." (PMID 35018490, 2022). "In addition, our results showed that KIF2C was higher in IDH1 wild-type samples than IDH1 mutant glioma samples, in 1p/19q noncodel samples than 1p/19q code glioma samples, and in recurrent samples than primary glioma samples." (PMID 35387222, 2022).
glioma (continued). "Furthermore, various animal models with IDH1 or IDH2 mutation recapitulated neurodegeneration, but not glioma genesis despite the epigenetic and transcriptomic resemblance." (PMID 35203456, 2022). "Interestingly, regardless of tumor grading, human glioma samples that were IDH1-wild-type (IDH1-WT) exhibited higher expression of TMEM158 than those with IDH1-mutant (IDH1-Mut)." (PMID 34992215, 2022). "Furthermore, the expression of TMEM158 was higher in IDH1-wt glioma samples compared to IDH1-mut irrespective of grade, and increased expression was correlated with poor OS in glioma patients." (PMID 36425564, 2022). "IDH1-wildtype status is required for GBM designation, and we selected these samples for the initial analysis to ensure any survival differences were not due to associations with glioma grade or IDH status." (PMID 35741006, 2022). "This may explain our results, probably because the similar high heterogeneity and aggressiveness of IDH1 wild-type gliomas, resulting in most parameters that do not differ significantly between LrGGs and GBMs both with wild-type IDH1." (PMID 34880724, 2021). "In addition, glioma with retained nuclear H3K27me3, loss of ATRX staining, and IDH1-R132H positivity can be predicted as 1p/19q non-codeleted glioma with a probability score of 0.9823." (PMID 34020723, 2021). "Finally, the Krebs cycle and fatty acid synthesis pathways play central roles in cellular metabolism; we also found that the IDH1, SDHB, FASN, ACACA, and ELOV2 genes were overexpressed, resulting in significant disturbances in the cellular metabolism of gliomas." (PMID 34573317, 2021). "In particular, gliomas lacking the IDH1/2 mutation (IDH-wt) of all grades II–IV were typed according to Verhaaks’ classification into classical (CL), mesenchymal (MES), proneural (PN), and neuronal (NL) gliomas." (PMID 34206856, 2021). "IDH1 is considered as a marker of secondary GBM and those primary GBMs diagnosed with IDH1 mutations may have been secondary gliomas that rapidly progressed to GBM with no early low-grade clinical symptoms experienced by patients." (PMID 34070746, 2021). "Furthermore, we called single nucleotide variants to confirm that mutations of the IDH1 and IDH2 genes, which are mutated in about 10% of human high-grade gliomas, had not spontaneously occurred during in vivo passaging and tumor development." (PMID 33435218, 2021). "Our analysis showed that GPX4, FSP1, GCH1, and DHODH were more highly expressed in tumor tissue than in non-tumor brain tissue, especially in high-grade, IDH1 wild type, 1p19q non-codeletion gliomas, suggesting that glioma cells had a strong potential to resist ferroptosis." (PMID 35174170, 2021). "Thus, they are associated with tumor progression and may be critical prognostic targets for gliomas with mutant PTEN, and more precisely in patients with IDH1-wt/PTEN-mut." (PMID 34336645, 2021). "Higher expression occurred in wild-type IDH-1 and 1p-19q non-codeletion glioma." (PMID 35087738, 2021). "Finally, driver gene analysis of the immune types revealed that IDH1, IDH2, and PLCH2 are the major driver genes for glioma, clearly suggesting that they may be potential targets for mRNA vaccines." (PMID 34603319, 2021). "Currently, systemically analysis of IDH1 in gliomas patients using IVIM has not been reported." (PMID 33795525, 2021).
glioma (continued). "In our study, we identified a unique subtype of gliomas based on the expression of ARLs, in which cluster 1 was associated with poor prognosis and enriched with the malignant subtype of gliomas including IDH1 wildtype, 1p19q non-codeleted, and MGMT unmethylated ones." (PMID 34211979, 2021). "Strikingly, long-term survivors from IDH1-R132H inhibition in combination with SOC and anti-PD-L1 immune checkpoint treatment group remained tumor-free post mIDH1 glioma rechallenging in the contralateral hemisphere, indicating the development of anti-mIDH1 glioma immunological memory." (PMID 34168976, 2021). "So, it is safe to suppose that IDH1 may affect SIX3 methylation and expression in glioma." (PMID 32051553, 2020). "It is worth noting that, by comparing the expression of SH3KBP1 in IDH1 wild-type and mutant groups, we observed that SH3KBP1 was highly expressed in wild-type IDH1 tumors, implying that SH3KBP1 may play critical roles in glioma progression." (PMID 33643898, 2020). "Furthermore, it was seen in our study that different combinations of IDH1/2 mutational statuses (irrespective of either wild or mutated) and MGMT methylation showed a better prognosis for survival in glioma patients." (PMID 33552543, 2020). "In addition to glioma cells, D2HG can be found in the non-neoplastic cells around the tumors in the patients carrying IDH1 mutation." (PMID 33221817, 2020). "Notably, by comparing the immune responses between IDH-1 MUT and IDH-1 WT patients, some studies have identified a marked reduction in the expression of immune-related genes, including the CD274 (PD-L1 coding gene) gene, in IDH-1 MUT gliomas." (PMID 33224142, 2020). "A previous study indicated that IDH1/2 mutation status alone was a predictive factor for longer overall survival and progression-free survival for the entire group of nonenhancing hemispheric grade II–III gliomas." (PMID 33489866, 2020). "Also, serum 2HG concentrations were in a similar range for gliomas with IDH1/2 mutations (33–283 ng/mL), and these were no different from those for patients with gliomas with wt IDH1/2 (35–277 ng/mL)." (PMID 31847543, 2020). "However, another study found that high TMB is only found in 3.5% of GBM patients, and that IDH1-mutant gliomas are not enriched for high TMB." (PMID 32986017, 2020). "However, treatment of preclinical orthotopic models of IDH1-mutant gliomas with AGI-5198 is not sufficient to reverse the mutant IDH-driven oncogenic changes such as DNA or histone methylation." (PMID 31652645, 2019). "However, IDH2/R140, unlike IDH1/R132 and IDH2/R172 mutations, is not found in gliomas, cholangiocarcinomas, and chondrosarcomas." (PMID 31817761, 2019). "Therefore, we focus exclusively on the roles of IDH1 and IDH2 in glioma biology in this article." (PMID 31263678, 2019). "However, although in vitro studies of the IDH1 inhibitors in gliomas have demonstrated a reduction in 2-HG, this has not been linked to response." (PMID 31795195, 2019). "However, after adjusting for sex, age group, and IDH1 mutation status, the PTPμ high non-GBM glioma patients had significantly longer recurrence free survival times than the PTPμ low non-GBM patients, 34.1 versus 11.8 months, respectively." (PMID 31091655, 2019). "Furthermore, mutant IDH1 decreases the HIF-1α-responsive gene, LDHA, which is essential for glycolysis and is overexpressed in cancers, through IDH-mutant-induced methylation of LDHA promoter, finally limiting the rapid cell growth of high-grade glioma." (PMID 31450721, 2019). "Accordingly, the Food and Drug Administration (FDA) has approved the mutant IDH1 inhibitor, ivosidenib, and IDH2 inhibitor, enasidenib for adults with relapsed or refractory acute myeloid leukemia, inhibitors of mutant IDH have entered clinical trials for glioma treatment." (PMID 30625996, 2019).
glioma (continued). "In lower grade IDH-1 (R132H) mutated astrocytomas without signs of neo-angiogenesis, SLUG and TWIST were absent on both IDH-1 (R132H)-mutated glioma cells and tumor-associated blood vessels." (PMID 29844871, 2018). "Oligodendroglioma (ODG) accounts for 5–9% of all gliomas (CBTRUS statistical report: NPCR and SEER; 2006–2010) and is classified by World Health Organization into IDH1 mutant and 1p/19q co-deleted grade II and IDH1 mutant and 1p/19q co-deleted anaplastic grade III ODGs." (PMID 29931616, 2018). "We performed profiling of IDH1/2 WT versus IDH1/2 mutant Grade II and III gliomas and identified transgelin-2 (TAGLN2), an oncogene and actin-polymerizing protein, to be expressed at significantly higher levels in IDH1/2 WT gliomas compared to IDH1/2 mutant gliomas." (PMID 30647847, 2018). "Furthermore, there has been a disappointment on the lack of glioma patient responses following IDH1 inhibitor treatments." (PMID 29439493, 2018). "The application of isocitrate dehydrogenase I R132H (IDH1 R132H) could differentiate low-grade gliomas from non-neoplastic CNS lesions." (PMID 30373180, 2018). "Interestingly, G0S2 mutations were not reported in 1102 gliomas among TCGA WHO grade II–IV gliomas, supporting the notion that G0S2 is epigenetically silenced in gliomas harboring IDH1 mutations." (PMID 30388142, 2018). "We observed that IDH1R132H was highly suppressive of subcutaneous tumor growth driven by platelet-derived growth factor B (PDGFB), but IDH1R132H tumor growth and glioma penetrance were virtually indistinguishable from those of IDH1-wildtype tumors in orthotopic models." (PMID 30416682, 2018). "Indeed, none of the mice (13/13) developed glioma with RCAS/IDH1R132H–PDGFB in contrast to 93% incidence (14/15) in those with RCAS/IDH1–PDGFB." (PMID 30416682, 2018). "Importantly, IDH1 wild-type and mutant gliomas are molecularly very different and comparative clinical outcome does not indicate how mutant IDH1 affects a tumor's response to treatment." (PMID 28178660, 2017). "While we could provide evidence that XAF1 methylation is strictly (100%) linked to 2-HG-producing mutations in IDH1 (shown for R132H, R132G) in grade III gliomas, we were not able to identify a less frequent IDH2-mutant tumor within the data set." (PMID 28122345, 2017). "Interestingly, we observed a significantly higher mean SWI-LIV in IDH1-R132H negative compared to IDH1-R132H positive gliomas." (PMID 27300198, 2017). "However, cells from the majority of IDH1 mutant gliomas do not grow in vitro and tumors passaged directly in mice do not consistently retain their original characteristics." (PMID 28178660, 2017). "Mutant IDH1 promotes checkpoint adaptation which can be exploited therapeutically with the combination of TMZ and a PLK1 inhibitor, indicating PLK1 inhibitors may be clinically valuable in the treatment of IDH1 mutant gliomas." (PMID 28178660, 2017). "• SWI-LIV is significantly increased in high-grade and IDH1-R132H negative gliomas." (PMID 27300198, 2017). "Significantly higher mean SWI-LIV values were found in HGG compared to LGG (92.7 versus 30.8; p < 0.0001), IDH1-R132H negative compared to IDH1-R132H positive gliomas (109.9 versus 38.3; p < 0.0001) and tumours with significant CE compared to non-significant CE (120.1 versus 39.0; p < 0.0001)." (PMID 27300198, 2017). "The first group had the longest median overall survival (96 months) in comparison with patients with IDH1 mutations and ATRX loss (51 months), while the shortest median overall survival was in glioma patients who did not harbor any of those signatures (13 months)." (PMID 27834917, 2016).